LYZ (lysozyme)
Diseases named in the same sentence as LYZ in open-access papers (continued):
Sharing a sentence is not in itself a finding about the gene and the disease.
hypernephroma (2 papers, 1976 to 2019). "IL2-XE114-TNFmut bound to SKRC52 renal cell carcinoma cell lines more intensely than IL2-KSF-TNFmut, which was specific to hen egg lysozyme and was chosen as a negative control of irrelevant specificity in the mouse." (PMID 31799191, 2019).
kidney failure (2 papers, 2017 to 2023). An acute or chronic condition that is characterized by the inability of the kidneys to adequately filter the blood. "Eight genes related to kidney toxicity, including kidney failure (CASP1, FCGR2A, FCGR2B, TLR2, TLR4, P = 0.003), damage of renal tubule (TLR2, TLR4, P = 0.01), proximal tubular toxicity (CTSS, LYZ, SLC22A5, P = 0.007) and their expression across 6 datasets were not confounded by tissue types." (PMID 28051114, 2017).
lymphopenia (2 papers, 2018 to 2023). Reduction in the number of lymphocytes. "First, it is well known that in dogs, as well as in other species, general leucocytosis, neutrophilia, lymphopenia, and eosinopenia occur during acute stress, as well as increases in serum and urine lysozyme levels during infections." (PMID 29596432, 2018).
nematode infection (2 papers, 2020 to 2025). "With regard to innate immune genes, cathelicidin 2, lysozyme, and saa were upregulated in the liver of immunized fish without live nematode infection." (PMID 40909269, 2025).
neuroblastoma (2 papers, 2013 to 2015). Neuroblastoma (NB) is the most common solid, extracranial childhood tumor. "For a more complete understanding of carnosine's mechanism of action in amyloid fibril inhibition, we have investigated the effect of the dipeptide on lysozyme fibril formation and induced cytotoxicity in human neuroblastoma SH-SY5Y cells." (PMID 24349167, 2013).
non-Hodgkin lymphoma (2 papers, 2025). Distinct from Hodgkin lymphoma both morphologically and biologically, non-Hodgkin lymphoma (NHL) is characterized by the absence of Reed-Sternberg cells, can occur at any age, and usually presents as a localized or generalized lymphadenopathy associated with fever and weight loss. "HS is diagnosed using positive immunohistochemistry for histiocytic markers, such as CD68, CD4, CD163, or lysozyme, and can present in an isolated form or be associated with other hematologic malignancies, such as non-Hodgkin lymphoma (NHL) or acute leukemia." (PMID 40066099, 2025). "Immunohistochemistry (IHC) is essential for accurate diagnosis, with MPO, lysozyme, and CD68 confirming myeloid lineage and excluding mimickers such as high-grade non-Hodgkin lymphomas." (PMID 40951125, 2025).
osteoarthritis (2 papers, 2016 to 2024). A noninflammatory degenerative joint disease occurring chiefly in older persons, characterized by degeneration of the articular cartilage, hypertrophy of bone at the margins and changes in the synovial membrane. "To address the role of macrophage PGAM5 in osteoarthritis, we generated Pgam5fl/fl -lyz2-Cre (Pgam5 cKO) mice, by crossing Pgam5fl/fl mice with transgenic mice that carried lysozyme (Lyz2) proximal promoter - mediated Cre recombinase, which specifically ablates PGAM5 from macrophages." (PMID 38433252, 2024).
osteosarcoma (2 papers, 2022 to 2023). A usually aggressive malignant bone-forming mesenchymal neoplasm, predominantly affecting adolescents and young adults. "Additionally, the scaffolds provided a release of lysozyme throughout the 21-day immersion time and decreased the proliferation of MG63 osteosarcoma cells due to the effect of lysozyme." (PMID 36976226, 2023).
pancreatic cancer (2 papers, 2021 to 2025). "B cells derived from MD4 mice have a fixed transgenic BCR that is reactive to hen egg lysozyme, therefore incapable of engaging host or pancreatic tumor-generated antigens." (PMID 35046933, 2021). "During the in-depth exploration of the pancreatic cancer microenvironment, four distinct cell populations were successfully identified and isolated, namely C0 RPS4Y1+ tumor cells, C1 LYZ+ tumor cells, C2 CPE+ tumor cells, and C3 MKl67+ tumor cells." (PMID 40230840, 2025).
pouchitis (2 papers, 2023 to 2024). Acute inflammation in the intestinal mucosa of the continent ileal reservoir (or pouch) in patients who have undergone ileostomy and restorative proctocolectomy (proctocolectomy, restorative). "More recently, the administration of exogenous lysozyme to rats with pouchitis has shown pouchitis amelioration associated with decreased TNF-α and IL-6 in the pouch tissue." (PMID 39770958, 2024). "There is a significant deficiency of Paneth cell-derived lysozyme granules in the rat model of pouchitis." (PMID 38137976, 2023). "Supplementation with exogenous lysozyme significantly ameliorated pouchitis, lowering the levels of inflammatory cytokines such as TNF-α and IL-6 in the pouch tissue." (PMID 38137976, 2023). "This study provides evidence of Paneth cell dysfunction and the downregulation of lysozyme in patients and a relevant animal model of pouchitis for the first time." (PMID 38137976, 2023). "Although the pouch tissue had a higher lysozyme mRNA level than the terminal ileum, pouchitis (PS) tissue has a lower lysozyme level compared to a normal pouch (NP) (1.35 ± 0.29 vs. 1.00 ± 0.00, p = 0.03; 0.78 ± 0.45 vs. 1.35 ± 0.29, p = 0.04, respectively)." (PMID 38137976, 2023). "Furthermore, IL1B/LYZ+ myeloid cells are responsible for reduced responses to vedolizumab in patients with pouchitis." (PMID 39770958, 2024). "The decreased secretion of lysozymes by Paneth cells might be one of the pathological characteristics of pouchitis, which also leads to a lower abundance of Lachnospiraceae that can be restored by oral lysozyme supplementation." (PMID 38137976, 2023). "We hypothesized that abnormal Paneth cell function, characterized by abnormal lysozyme secretion, triggered microbiota dysbiosis to aggravate pouchitis." (PMID 38137976, 2023). "The effect of exogenous lysozyme supplementation on pouchitis was also investigated." (PMID 38137976, 2023). "Thus, Paneth cell dysfunction might be a new mechanism of pouchitis, in line with other studies on lysozyme supplementation for treating intestinal inflammation." (PMID 38137976, 2023). "Although Paneth cell dysfunction has been observed in the pathology of ileitis, aberrant lysozyme production in pouchitis has not been elucidated." (PMID 38137976, 2023).
protein misfolding disease (2 papers, 2020 to 2024). "Systemic ALys amyloidosis is a debilitating protein misfolding disease that arises from the formation of amyloid fibrils from C-type lysozyme." (PMID 39511224, 2024). "Lysozyme is a vital component of the human innate immune system, although it may also form the basis of a debilitating protein misfolding disease." (PMID 39511224, 2024).
psoriasis (2 papers, 2021 to 2022). An autoimmune condition characterized by red, well-delineated plaques with silvery scales that are usually on the extensor surfaces and scalp. "Increased levels of amylase, Na+ and IgA in patients with psoriasis, as well as reduced lysozyme levels." (PMID 35454992, 2022). "Psoriasis patients had a lower concentration and secretion rate of IgA and lysozyme than controls." (PMID 35454992, 2022).
pulmonary sarcoidosis (2 papers, 2016 to 2025). Sarcoidosis affecting the lung parenchyma. "Previous studies have demonstrated the correlations of serum levels of inflammatory chemokines and cytokines with serum ACE and lysozyme activities in patients with ocular and pulmonary sarcoidosis." (PMID 26879979, 2016). "Among the top 13 biomarkers with an AUC > 0.90, plasma lysozyme (P61626, encoded by the LYZ gene) and toll-like receptor 8 (Q9NR97, encoded by the TLR8 gene) have been identified as diagnostic biomarkers specifically for pulmonary sarcoidosis 55 and cardiac sarcoidosis 56, respectively." (PMID 41279897, 2025). "Serum concentrations of IL-12 p40 have been found significantly higher in pulmonary sarcoidosis than healthy subjects and have been correlated with serum levels of ACE and lysozyme." (PMID 26879979, 2016).
Salmonella Infections (2 papers, 2024 to 2026). Infections with bacteria of the genus SALMONELLA. "Recombinant typhoid toxin or Salmonella infection recapitulated LYZ and APOC3 secretion in cultured cells, which involved ATM/ATR-dependent DDRs and confirmed observations in typhoid fever." (PMID 41326716, 2026). "We then investigated how Lyz1−/− mice, which lack the intestinal lysozyme, would respond to Salmonella infection." (PMID 38823640, 2024). "Here, we demonstrated that during Salmonella infection, lysozyme overexpression increased bacterial invasion and the inflammatory response, whereas Lyz1 deficiency significantly protected against pathogen-induced inflammatory response." (PMID 38823640, 2024). "To determine the impact of lysozyme overproduction on Salmonella infection, we inoculated S. Typhimurium (SL1344) to WT and Villin-Lyz1TG mice (all on C57BL/6 background)." (PMID 38823640, 2024). "Single-cell (sc)RNA-Seq analysis demonstrated that Salmonella infection robustly suppressed lysozyme RNA abundances in Paneth cells." (PMID 38823640, 2024). "The observed reduction of lysozyme expression in Paneth cells in response to Salmonella infection shown by us and others may reflect an adaptive protection by the host." (PMID 38823640, 2024).
Sanfilippo syndrome type B (2 papers, 2012 to 2020). "Prior work on Sanfilippo syndrome type B has shown although lysozyme expression is ubiquitous, lysozyme protein accumulates specifically in disease susceptible neurons, and this group correlated lysozyme protein expression with formation of hyperphosphorylated tau in the same neurons." (PMID 32731618, 2020). "Elevated lysozyme transcripts and protein have been found in neuronal cells in the brain of another lysosomal disorder mouse model Sanfilippo syndrome type B (also known as MPS IIIB)." (PMID 23094108, 2012).
septic arthritis (2 papers, 2022 to 2024). "In a local septic arthritis model, a S. aureus strain deficient in peptidoglycan o-acetyltransferase, which is highly sensitive to lysozyme secreted by phagocytes, exhibited attenuated virulence in inducing septic arthritis." (PMID 38410388, 2024). "Bennett compared the lysozyme levels of SF in patients with traumatic effusions, OA, RA, pseudogout, septic arthritis, and gout, and the results showed that elevated lysozyme levels were found in all the IA." (PMID 35359923, 2022).
Stroke (2 papers, 2023 to 2025). Sudden impairment of blood flow to a part of the brain due to occlusion or rupture of an artery to the brain. "In a study using an adult rat model of MCAO to simulate stroke, pH-sensitive polymeric micelles loaded with lysozyme (lysozyme-pH-PM) and SDF-1α (SDF-1α-pH-PM) were administered intravenously and effectively delivered the target proteins to the ischaemic site." (PMID 40558537, 2025). "Notably, stroke did not induce changes in Defa (for α-defensin) and Lyz1 (for lysozyme) genes in any of the groups (data not shown)." (PMID 37910478, 2023).
thyroid cancer (2 papers, 2024 to 2025). "Similarly with previous study that revealed that activated neutrophils enhance their lysozyme release by crosslinking of CD69, our data revealed that CD69 expression in neutrophils is associated with immunosuppressive phenotype in thyroid cancer." (PMID 38719807, 2024).
tubulointerstitial nephritis (2 papers, 2024 to 2025). "Most included studies reported renal biopsy findings of tubulointerstitial nephritis, with abundant eosinophilic cytoplasmic droplets staining positively for lysozyme." (PMID 41181405, 2025).
type 1 diabetes (2 papers, 2014 to 2021). "Perturbation of mitochondrial membranes is also found in non-neuropathic amyloidoses, including lysozyme systemic amyloidosis, T2D and type I diabetes (T1D)." (PMID 33791300, 2021).
acute leukemia (1 paper, 2025). A clonal (malignant) hematopoietic disorder with an acute onset, affecting the bone marrow and the peripheral blood. "Myeloperoxidase (MPO)/lysozyme (LYZ) and marginal zone B and B1 cell-specific protein (MZB1)/brain and acute leukemia, cytoplasmic (BAALC) were respectively activated in the granulocyte-macrophage progenitor (GMP) and multilymphoid progenitor (MLP) clusters." (PMID 40036065, 2025).
acute monocytic leukemia (1 paper, 2021). Acute monoblastic leukemia (AML-M5), is one of the most common subtypes of acute myeloid leukemia (AML) that is either comprised of more than 80% of monoblasts (AML-M5a) or 30-80% monoblasts with (pro)monocytic differentiation (AML-M5b). "CD68, lysozyme, and myeloperoxidase are the most sensitive immunohistochemical markers for detecting monoblasts (acute monocytic leukemia 5) or myelomonoblasts (acute monocytic leukemia 4), which account for the vast majority of leukemias at this age." (PMID 34449594, 2021).
allergic rhinitis (1 paper, 2024). Inflammation of the nasal mucous membranes caused by an IgE-mediated response to external allergens. "This May be attributed to the lysozyme contained in cheese, which is a potential food allergen that can sensitize individuals to develop allergic rhinitis upon consumption." (PMID 39399526, 2024).
bacterial meningitis (1 paper, 2025). Inflammation of the membranes surrounding the brain and spinal cord due to a bacterial infection. "neuro-Behçet’s disease (neopterin), neurotuberculosis, CNS lymphoma (sIL-2R), and bacterial meningitis (lysozyme)." (PMID 39812656, 2025).
bacterial pneumonia (1 paper, 2024). Acute infection of the lung parenchyma caused by bacteria (e.g., Streptococcus pneumoniae, Haemophilus influenzae, Chlamydia pneumoniae, Mycoplasma pneumoniae, and Legionella pneumophila). "In this study, we investigated the role of lysozyme-regulated gut microbiota and explored the potential therapeutic effects of lysozyme on ileum injury induced by sTBI and bacterial pneumonia through in vivo and in vitro experiments." (PMID 38352055, 2024). "The current study sought to clarify the role of lysozyme-regulated gut microbiota and explored the potential therapeutic effects of lysozyme on ileum injury induced by severe traumatic brain injury (sTBI) and bacterial pneumonia in vivo and in vitro experiments." (PMID 38352055, 2024).
Barrett esophagus (1 paper, 2021). Esophageal lesion lined with columnar metaplastic epithelium which is flat or villiform. "Compared with normal tissues, the levels of lysozyme in Barrett’s esophageal columnar epithelial cells were significantly increased, suggesting that lysozyme may be involved in the formation of Barrett’s esophagus." (PMID 34925025, 2021).
bone tumor (1 paper, 2019). "Concerning these data, we chose to use a concentration of 1200 μg/mL, considering the fact that our scaffolds are intended for bone tumor treatment and an elevated level of lysozyme will be found in the bone." (PMID 31108965, 2019).
breast tumors (1 paper, 2021). "Previous research of the breast milk protein in breast tumors showed an inverse relationship between cancer severity and increased expression of LYZ." (PMID 34189853, 2021).
bronchiectasis (1 paper, 2023). Segmental, irreversible dilation of the bronchial tree resulting in the accumulation of secretions which leads to obstruction. "One study suggested that in patients with bronchiectasis, the impairment physical and immune barriers of the airway wall lead to a decrease in the function of phagocytic cells in airway secretions, resulting in opportunistic NTM infections due to insufficient secretion of lysozyme." (PMID 37986162, 2023).
bronchiolitis (1 paper, 2023). Inflammation of the bronchioles characterized by swelling of the bronchioles and mucus accumulation. "Breast milk contains high levels of lysozyme and immune factors that significantly reduce the production of IgE in the organism, which in turn reduces the chances of bronchiolitis." (PMID 37389334, 2023).
bronchopulmonary dysplasia (1 paper, 2018). Bronchopulmonary dysplasia is a chronic respiratory disease that results from complications related to lung injury during the treatment of infant acute respiratory distress syndrome in low-birth-weight premature infants or from abnormal lung development in older infants. "Among several protein biomarkers, the role of lysozyme has been found to be especially important in human immune system to prevent several bacterial infections and other chronic disease such as bronchopulmonary dysplasia." (PMID 29662878, 2018).
brucellosis (1 paper, 2024). Brucellosis is a bacterial infection that spreads from animals to people via unpasteurized dairy products or by exposure to contaminated animal products or infected animals. "The findings demonstrated that while these proteins were elevated during the acute phase of Brucellosis, CRP, FGB, LYZ, and AAT did not return to the baseline levels observed in healthy controls in chronic patients." (PMID 39872944, 2024).
cardiac sarcoidosis (1 paper, 2020). Sarcoidosis affecting the tissues of the heart. "LYZ levels were elevated in cardiac sarcoidosis patients with intractable heart failure and refractory arrhythmias." (PMID 33041871, 2020).
chlamydiaceae infections (1 paper, 2019). Infections with bacteria of the family CHLAMYDIACEAE. "Innate responses to Chlamydiaceae infection include initial local recruitment of leukocytes to the site of infection and the production of pro-inflammatory cytokines and chemokines including lysozyme." (PMID 31231361, 2019).
cholestasis (1 paper, 2021). Impairment of the bile flow caused by obstruction within the liver, or outside the liver in the bile duct system. "In the acute exposure to this toxin, an inflammatory response of neutrophils, lysozyme and calprotectin in KCs was observed in areas of cholestasis." (PMID 33918904, 2021). "An increase in the number of macrophages and PMNs that stained positively for both anti-lysozyme and anti-MAC387 antibodies was observed in the areas of canalicular cholestasis and hepatocyte necrosis in acute FE liver lesions." (PMID 33918904, 2021).
chronic gastritis (1 paper, 2014). Inflammation of the stomach that is chronic in nature. "In chronic gastritis lysozyme is up-regulated in the neck region of the oxyntic mucosa, in antral pyloric glands and in the surface-foveolar epithelium of the oxyntic mucosa." (PMID 25437608, 2014).
chronic hepatitis (1 paper, 2025). An active inflammatory process affecting the liver for more than six months. "Recent research suggested an additional immunomodulatory function for lysozyme, with serum levels elevated in patients with primary biliary cirrhosis and chronic hepatitis." (PMID 40565363, 2025).
coccidiosis (1 paper, 2018). A parasitic infection caused by Coccidia. "In the current study, the concentration of serum lysozyme was about 35% lower in chickens vaccinated against coccidiosis, indicating that the period of vaccination +14 d was not sufficient for a return to homeostasis." (PMID 30445686, 2018).
collagenous colitis (1 paper, 2014). A type of microscopic colitis of unknown etiology. "In collagenous colitis lysozyme is up-regulated in the colonic crypts and in metaplastic Paneth cells." (PMID 25437608, 2014). "The increased production of lysozyme in collagenous colitis and in lymphocytic colitis supports a bacterial aetiology for these two diseases." (PMID 25437608, 2014). "The different mucosal cell types displaying increased production of lysozyme (epithelial vs. macrophages) substantiates the notion that collagenous colitis and lymphocytic colitis might be two different diseases." (PMID 25437608, 2014).
Crohn's colitis (1 paper, 2014). Crohn's disease affecting the colon. "In Crohn’s colitis lysozyme up-regulation is found in metaplastic Paneth cells (left colon), in the crypts as well as in the lamin propria mucosae." (PMID 25437608, 2014).